COMMD10 (COMM domain containing 10)
Diseases named in the same sentence as COMMD10 in open-access papers:
COMMD10 is named in the same sentence as 22 diseases in open-access papers, as found by Europe PMC text mining. Sharing a sentence is not in itself a finding about the gene and the disease. The quoted sentences say what the papers report.
colorectal cancer (11 papers, 2019 to 2024). A primary or metastatic malignant neoplasm that affects the colon or rectum. "COMMD10 was shown to inactivate NF-κB signaling pathway in colorectal cancer and hepatocellular carcinoma, thereby inhibiting the development of these tumors." (PMID 38871970, 2024). "It has been demonstrated that COMMD10 can inhibit invasion and metastasis of colorectal cancer by targeting the p65 nuclear factor-kappaB (NF-kappaB) subunit and reducing its nuclear translocation, which leads to inactivation of the NF-kappaB pathway." (PMID 36919165, 2023). "In recent years, the relationship between COMMD10 and colorectal cancer and liver cancer has been reported." (PMID 36919165, 2023). "COMMD10 hinders the development of colorectal cancer and hepatocellular carcinoma." (PMID 38871970, 2024). "COMMD10 can suppress invasion and metastasis of colorectal cancer by regulating NF-κB pathway." (PMID 35399735, 2022). "Additionally, we found that COMMD10 inhibited the invasiveness and metastasis of colorectal cancer." (PMID 34047468, 2021). "COMMD10 is a relatively common COMMD protein, which can inhibit invasion and metastasis of colorectal cancer by regulating NF-κB pathway." (PMID 35399735, 2022). "COMMD10 is a common member of the COMMD family which suppresses the invasiveness and metastatic properties of colorectal cancer cells through NF-κB." (PMID 36092163, 2022).
hepatocellular carcinoma (6 papers, 2021 to 2025). A malignant tumor that arises from hepatocytes. "Although COMMD10 is known for its role in copper–iron homeostasis and radio-resistance in hepatocellular carcinoma, the functional role of COMMD3 in MM has remained unexplored." (PMID 40002764, 2025). "For instance, radiotherapy induces a decrease in COMM domain-containing 10 (COMMD10), leading to intracellular copper accumulation and radio-resistance in hepatocellular carcinoma." (PMID 38844964, 2024). "It has also been shown that in hepatocellular carcinoma, COMMD10 inhibits HIF1α/CP positive feedback loop to enhance radiosensitivity by disrupting Cu-Fe balance." (PMID 36919165, 2023). "Whereas previously in both colorectal and hepatocellular carcinomas, COMMD10 has a cancer suppressive effect, which reflects the differences of the role played by COMMD10 in different cancers, and the specific mechanisms need to be further explored." (PMID 36919165, 2023). "In a recent investigation on hepatocellular cancer, COMMD10 was also discovered to bind and inhibit HIF-1α, and it has to be determined if additional members of the COMMD protein family have comparable effects." (PMID 36776284, 2023). "COMMD10/NF‐κB axis promotes apoptosis by modulating Bcl‐2/Bax/caspase‐9/3 pathway in hepatocellular carcinoma." (PMID 34047468, 2021). "Moreover, COMMD10 can enhance ferroptosis by disturbing the balance of Cu and Fe, thus increasing the radiosensitivity of hepatocellular carcinoma." (PMID 38871970, 2024).
gastric cancer (4 papers, 2023 to 2024). A primary or metastatic malignant neoplasm involving the stomach. "The results from cell proliferation assay and clone formation assay demonstrated that upregulation of COMMD10 significantly enhanced the capacities of proliferation and clone formation of gastric cancer cells." (PMID 38871970, 2024). "Given the indication of poor prognosis in gastric cancer patients with high COMMD10 expression, we conducted further molecular biology experiments to validate the potential mechanism of COMMD10." (PMID 38817875, 2024). "This suggests that SC79 can attenuate the inhibitory effect of COMMD10 knockdown on the phosphorylation expression of key proteins in the AKT pathway of gastric cancer cells." (PMID 38817875, 2024). "Functional experiments revealed a decline in the proliferative and migratory capabilities of gastric cancer cells upon silencing COMMD10." (PMID 38817875, 2024). "To accentuate the translational medical value of the COMMDs family, we selected COMMD10 as a differential gene in gastric cancer for further validation." (PMID 38817875, 2024). "Kaplan-Meier (K-M) analysis was conducted for each COMMD gene in gastric cancer tissues, revealing COMMD1 and COMMD10 as significant high-risk factors for overall survival (OS) in gastric cancer patients." (PMID 38817875, 2024). "COMMD10 has an important role in the development of certain tumors, but its relevance to gastric cancer (GC) is unclear." (PMID 36919165, 2023). "Additionally, through pathway intervention, we unveiled the PI3K-AKT pathway as a potential mechanism through which COMMD10 influences gastric cancer activity." (PMID 38817875, 2024). "Our analysis of COMMDs family genes suggested that COMMD10 might be a crucial molecule influencing the malignant progression of gastric cancer." (PMID 38817875, 2024). "However, COMMD10 is not currently studied in gastric cancer (GC)." (PMID 36919165, 2023).
liver cancer (4 papers, 2023 to 2025). An epithelial or non-epithelial malignant neoplasm that arises from the liver. "Subsequent research demonstrated that COMMD10 regulates radiation resistance in liver cancer cells by reducing intracellular copper levels and inducing ferroptosis." (PMID 38817875, 2024). "COMMD10 is modestly expressed in liver cancer and can disrupt the NF‐κB signaling pathway, reduce proliferation, increase apoptosis, and improve the predictive value of BCLC staging." (PMID 36205192, 2023). "COMMD10, in contrast to COMMD1, has been extensively studied in the context of liver cancer." (PMID 38817875, 2024). "In addition, COMMD10 was closely correlated with barcelona clinic liver cancer (BCLC) staging in predicting OS, providing important evidence for identifying potential therapeutic targets and accurately predicting prognosis in patients with liver cancer." (PMID 40433591, 2025).
chronic obstructive pulmonary disease (2 papers, 2019 to 2021). A chronic and progressive lung disorder characterized by the loss of elasticity of the bronchial tree and the air sacs, destruction of the air sacs wall, thickening of the bronchial wall, and mucous accumulation in the bronchial tree. "In addition, genome‐wide analysis showed that COMMD10 was a novel biologically relevant associated with systemic inflammation before fenofibrate treatment, and single nucleotide polymorphisms in the COMMD10 loci was associated with both asthma and chronic obstructive pulmonary disease." (PMID 34047468, 2021).
colon cancer (2 papers, 2020 to 2023). "Based on the role of COMMD10 in GI-related tumors such as liver and colon cancers, we sought to explore whether it also plays an important role in GC." (PMID 36919165, 2023).
colitis (1 paper, 2018). Inflammation of the colon. "Therefore, we next studied the effect of COMMD10-deficiency in myeloid cells on intestinal inflammation in an acute model of dextran sodium sulfate (DSS)-induced colitis." (PMID 30487795, 2018). "Our results mark COMMD10 as a negative regulator of inflammasome activity in these cells in the context of colitis as well." (PMID 30487795, 2018). "In the setting of colitis, we demonstrate that disrupted COMMD10 activity unleashes the inflammatory behavior of circulating Ly6Chi monocytes." (PMID 30487795, 2018). "Furthermore, Commd10 gene expression was also profoundly reduced in the transition of Ly6Chi monocytes from circulation (splenic reservoir) to colonic tissue in the context of colitis." (PMID 30487795, 2018). "We show that COMMD10-deficiency dramatically augments canonical and non-canonical inflammasome activation in Ly6Chi monocytes, but not tissue-resident macrophages, thus fueling inflammation in mice with LPS-induced systemic inflammation or colitis." (PMID 30487795, 2018). "Finally, COMMD10 expression was reduced in Ly6Chi monocytes and their corresponding human CD14hi monocytes sorted from mice subjected to DSS-induced colitis or from IBD patients, respectively." (PMID 30487795, 2018). "The results above highlight an important negative immunoregulatory role for COMMD10 in tuning Ly6Chi monocyte-driven inflammation during colitis." (PMID 30487795, 2018). "The increased colitis score observed in the LysMΔCommd10, but not in Cx3cr1ΔCommd10 mice, further substantiates that COMMD10-governed immunoregulation is important already at the level of these circulating monocytes." (PMID 30487795, 2018). "Notably, the colitis score of Cx3cr1ΔCommd10 mice was similar to that of Commd10fl/fl control mice, suggesting that COMMD10 does not play a critical anti-inflammatory role in CX3CR1hi lpMFs." (PMID 30487795, 2018). "Indeed, in comparison to Ly6Chi monocytes sorted from steady state splenic reservoirs, there was a profound decrease in the transcription of Commd10 in their Ly6Chi monocyte counterparts sorted from splenic reservoirs and inflammatory colons at day 4 of DSS-induced colitis." (PMID 30487795, 2018). "In consistence with these results, COMMD10-deficiency in Ly6Chi monocytes, but not in intestinal-resident lamina propria macrophages, led to increased IL-1β production and aggravated colonic inflammation in a model of DSS-induced colitis." (PMID 30487795, 2018).
E. coli infection (1 paper, 2018). "Here we show that COMMD10-deficiency in Ly6Chi monocytes and their macrophage descendants, as well as in their human CD14hi monocyte equivalents, leads to increased and persistent activation of NF-κB in response to LPS or E. coli infection." (PMID 30487795, 2018).
gastric adenocarcinoma (1 paper, 2023). "The purpose of this study is to investigate the difference of COMMD10 expression in gastric adenocarcinoma (STAD) and analyze the correlation between COMMD10 expression and prognosis of STAD patients." (PMID 36919165, 2023).
Gilbert syndrome (1 paper, 2021). An autosomal recessive inherited disorder characterized by unconjugated hyperbilirubinemia, resulting in harmless intermittent jaundice. "Array-CGH showed two intronic deletions involving MACROD2 and COMMD10 genes, which could be related to a congenital heart defect; whole exome sequencing highlighted the genotype compatible with Gilbert syndrome." (PMID 34829491, 2021).
renal clear cell carcinoma (1 paper, 2023). "COMMD10 is highly expressed in renal clear cell carcinoma and predicts better overall survival of patients." (PMID 36776284, 2023). "Bioinformatics analysis revealed that the expression of COMMD10 in lung squamous cell carcinoma, breast invasive carcinoma, and renal clear cell carcinoma is distinct from that of their corresponding normal tissues." (PMID 36776284, 2023). "Moreover, high COMMD10 expression in renal clear cell carcinoma is predictive with improved patient survival." (PMID 36776284, 2023).
Sepsis (1 paper, 2018). Sepsis is defined as life-threatening organ dysfunction caused by a dysregulated host response to infection. "Collectively, these findings mark an important role for COMMD10 in the protection of intestinal barrier function from Ly6Chi monocyte-driven inflammation during sepsis." (PMID 30487795, 2018).
tumor (10 papers, 2018 to 2025). "The results showed that high expression of COMMD10 was significantly associated with T stage (p < 0.05), residual tumor (p < 0.001), and OS events (p < 0.05) in these patients." (PMID 36919165, 2023). "As a member of the copper metabolism MURR1 domain (COMMD) family, COMMD proteins have been implicated in regulating intracellular copper ion levels, with COMMD10 previously shown to influence copper metabolism in tumor cells." (PMID 40002764, 2025). "The effect of COMMD10 knockdown was investigated in the GC cell lines and in in vivo xenograft tumor experiments." (PMID 38871970, 2024). "We further evaluated the mRNA expression levels of COMMD10 in cancer and paracancerous tissues of STAD patients, and the results showed that the expression levels of COMMD10 were significantly higher in tumor tissues than in paracancerous tissues (p < 0.01)." (PMID 36919165, 2023). "The capability of COMMD10 to suppress HCC progression was further examined using a xenograft tumor model." (PMID 34047468, 2021). "COMMD1, COMMD5, and COMMD10 are known to act as tumor suppressors, and their expression levels are reduced in several cancers including cancers, seminoma, melanoma, as well as kidney, pancreatic, colorectal, and ovarian cancers." (PMID 34943955, 2021). "Multivariate Cox regression analysis revealed that COMMD10, age, tumor size, tumor embolus, and ALB remained strong and independent prognostic factors for OS in the NF training cohort." (PMID 34047468, 2021). "In the present study, COMMD10 was more highly expressed in HCC tissues than in normal tissues and was associated with the patients’ individual cancer stage and tumor grade." (PMID 34493238, 2021). "COMMD10 is initially identified as a tumor regulator in the pathogenesis of multiple human tumors in our observations." (PMID 34047468, 2021). "COMMD10 downregulation significantly suppressed the growth of xenograft tumor." (PMID 38871970, 2024). "Moreover, the knockdown of COMMD10 suppressed the growth of GC xenograft tumors and hindered DNA repair while promoting DNA damage in transplanted tumor tissues." (PMID 38871970, 2024). "Unsurprisingly, the tumor volume and weight were also reduced in the COMMD10 knockdown group." (PMID 38871970, 2024). "Using the TCGA database, we found that COMMD10 expression was positively correlated with tumor T-stage and residual tumor, suggesting that COMMD10 may be involved in the infiltrative growth of STAD." (PMID 36919165, 2023). "Specifically, the relationship between COMMD10 expression and ten clinicopathological characteristics of GC patients were investigated, including age, gender, H. pylori infection, T-stage, N-stage, M-stage, pathological stage, residual tumor and OS events." (PMID 36919165, 2023). "Finally, the relationship between COMMD10 expression and tumor immune infiltration was investigated." (PMID 36919165, 2023). "Moreover, our previous study elucidated the functions of COMMD10 in various human tumors based on expression profile and bioinformatics analysis, indicating its valuable role in the development and progression of tumor." (PMID 34047468, 2021). "COMMD10 as well inhibits NF-kB acting as a tumor suppressor, as shown with colorectal cancer." (PMID 34943955, 2021). "In addition, high expression of COMMD10 negatively correlated with tumor size while positively correlated with tumor differentiation in training cohort." (PMID 34047468, 2021). "Moreover, IHC staining results showed that COMMD10 expression was remarkably reduced in tumor regions compared to that in healthy human liver." (PMID 34047468, 2021). "Considering our study involves tumor immunity and previous research on the impact of the PI3K pathway on immunotherapy, we contemplate the future potential application of COMMD10 in immunotherapy, which requires further investigation." (PMID 38817875, 2024).
tumor (continued). "The expression of COMMD10 was upregulated in GC compared to that in para-cancerous tissue and correlated with a higher clinical TNM stage (P = 0.044) and tumor size (P = 0.0366)." (PMID 38871970, 2024). "Given the critical role of the TME in mediating cancer progression and the fact that tumor-infiltrating immune cells are an integral component of the TME, we sought to investigate the relationship between COMMD10 and immune infiltration in STAD." (PMID 36919165, 2023). "At present, there is no report on the relationship between COMMD10 and tumor immune infiltration and m6A modification." (PMID 36919165, 2023).
cancer (7 papers, 2019 to 2024). A tumor composed of atypical neoplastic, often pleomorphic cells that invade other tissues. "COMMD10 expression was significantly associated with multiple cancers, including STAD in TCGA." (PMID 36919165, 2023). "Western blotting was also used to detect the expression of COMMD10 in 10 pairs of cancer and paracancerous tissues." (PMID 36919165, 2023). "The dot blot experiment showed that m6A levels were higher in cancer tissues with high COMMD10 expression compared with paracancerous tissues." (PMID 36919165, 2023). "The results showed that the expression of COMMD10 was higher in cancer than in paracancerous tissues." (PMID 36919165, 2023). "We observed that COMMD10 protein levels were higher in most cancer tissues than in paired paracancerous tissues." (PMID 36919165, 2023). "Kyoto Encyclopedia of Genes and Genomes (KEGG) enrichment analysis of COMMD10 and its and its interacted genes showed that they were significantly enriched in pathways in cancer, hypoxia-inducible factor signaling, ubiquitin-mediated proteolysis, endocytosis, renal cell carcinoma and mineral uptake." (PMID 38871970, 2024). "Since the COMMD family members COMMD1 and COMMD4 had been reported to be involved in DNA damage repair to maintain the genome stability of the cancer cells, we wondered whether COMMD10 plays a role in DNA damage in GC cells." (PMID 38871970, 2024). "COMMD10 expression was elevated in STAD cancer tissues compared to paracancerous tissues." (PMID 36919165, 2023). "Data downloaded from TCGA and GTEx were used to analyze the expression of COMMD10 in pan-cancer." (PMID 36919165, 2023). "Similar to COMMD1, COMMD10 plays a role in cancer by targeting the NF-κB pathway." (PMID 34493238, 2021).
psychiatric disorder (1 paper, 2022). A disorder characterized by behavioral and/or psychological abnormalities, often accompanied by physical symptoms. "Other variants were located in intergenic regions or in genes that have not been previously associated with psychiatric disorders (e.g., COMMD10) or for which the function is not yet known (RP11-25I11.1)." (PMID 36422266, 2022).
COMMD10 also shares sentences with these, for which no sentence is quoted: alcoholic liver diseases (1 paper); amyotrophic lateral sclerosis (1); asthma (1); hepatitis C virus infection (1); non‐alcoholic steatohepatitis (1); osteosarcoma (1); systemic lupus erythematosus (1).